RACK1 (receptor for activated C kinase 1)
Diseases named in the same sentence as RACK1 in open-access papers (continued):
Sharing a sentence is not in itself a finding about the gene and the disease.
cancer (111 papers, 2005 to 2026). A tumor composed of atypical neoplastic, often pleomorphic cells that invade other tissues. "The precise regulation of these signaling hubs is critical for normal physiology, and their dysregulation is frequently implicated in pathological states such as cancer, where RACK1 often exhibits altered expression and function." (PMID 41373878, 2025). "Since RACK1 expression is associated with immune cell function as well as cytokine production and has a dual role in immunity and cancer, we performed relevant animal and immune experiments, including the detection of PD‐1/L1 immune checkpoints and cytokines." (PMID 38451046, 2024). "In cancers like colorectal, breast, and lung cancer, RACK1 is frequently overexpressed, which is linked to more aggressive tumors and worse outcomes for patients." (PMID 39458945, 2024). "The pooled results indicated that high RACK1 expression in patients with cancer was associated with lymphatic invasion/N+ stage (OR = 1.74; 95% CI [1.04–2.90]; P = 0.04; I2 = 79%) of tumors." (PMID 37601269, 2023). "The receptor for activated C kinase 1 (RACK1) expression is associated with clinicopathological characteristics and the prognosis of various cancers; however, the conclusions are controversial." (PMID 37601269, 2023). "The results of the association between RACK1 expression and lymphatic invasion/ N + stage regarding specific cancer types." (PMID 37601269, 2023). "As a signaling hub, RACK1 has been associated with the activation of several cancer-related cellular signaling pathways, including PKC, receptor tyrosine kinase/PI3K/AKT, ERK/MAPK, integrin/Src/FAK, WNT/β-catenin, STAT3, and RhoA/Rho pathways." (PMID 37848434, 2023). "Thirteen studies and 2,620 patients were included in the meta-analysis to assess the association between RACK1 expression and the prognosis of patients with cancer." (PMID 37601269, 2023). "EN0 showed higher expression of ACKR1 (logFC = 1.2), carcinoma-associated genes RACK1 (logFC = 0.7) and CD74 (logFC = 0.8)." (PMID 38328306, 2023). "In metazoa, RACK1 is crucial for embryogenesis, and aberrant expression levels of RACK1 are associated with poor clinical outcome of different types of cancers." (PMID 34769086, 2021). "RACK1 or TRAF2 is an apoptotic molecule inactivated by SGs cause to impede cancer cell resistance to bortezomib." (PMID 35004322, 2021). "We proposed that Anxa2 functions downstream of Rack1 to promote the aggressive behavior in drug-resistant cells given that Rack1 binds and regulates Anxa2 phosphorylation, and Anxa2 is a key protein causing drug resistance and enhancement of cancer metastasis." (PMID 31113450, 2019). "Multiple studies have demonstrated that the association between RACK1 and β1/β2 integrin and between RACK1 and c-Src regulates cell adhesion and cell motility in cancer cells." (PMID 31358728, 2019). "Because one of the cancer-associated mutations involved the same residue (ΔS1278), we measured the coimmunoprecipitation of endogenous RACK1 with wild-type and mutant forms of IGF1R in R-minus cells." (PMID 22778948, 2012). "RACK1 is also implicated as a key player in ovarian cancer, prostate cancer and in cancers caused by pathogens such as human papillomavirus 16 (HPV 16) and Helicobacter pylori." (PMID 21978545, 2011). "The expression of RACK1 appears to be tightly regulated and changes in RACK1 expression are associated with cancer (see section 6.1)." (PMID 21978545, 2011). "RACK1’s interaction with key surface receptor proteins leads to the activation of a kinase associated with M2 macrophage polarity—a key event in stimulating cancer cell migration and invasion." (PMID 40940922, 2025). "Numerous studies reported that RACK1 is associated with EMT in cancer cells." (PMID 40940922, 2025). "Loss of SMURF2 stabilizes RACK1, promoting cancer cell survival and proliferation." (PMID 39697237, 2024).
cancer (continued). "Notably, previous studies reported RACK1 to be closely associated with the prognosis of patients with cancer because of its involvement in several tumor-related signaling pathways, such as the Src/FAK, AKT/mTOR, IKK/NF-κB, and Wnt/ β-catenin pathways." (PMID 37601269, 2023). "Dysregulation of RACK1 has been implicated in the initiation and progression of various cancers." (PMID 37848434, 2023). "Increased RACK1 expression was significantly associated with lymphatic invasion, which might account for the poorer survival rate in RACK1-high patients with cancer." (PMID 37601269, 2023). "Consistently, cancer patients with higher RACK1 expression are associated with poor prognosis." (PMID 37848434, 2023). "Considering that different cancer types may have different propensities for lymphatic invasion, we analyzed the association between RACK1 expression and lymphatic invasion in specific cancer types." (PMID 37601269, 2023). "Therefore, the roles and the underlying signaling mechanisms of Rack1 in different types of human cancers warrant further investigation." (PMID 34480519, 2021). "Another study reported that RACK1 expression levels were higher in normal breast tissues than in cancer specimens; however, this study also reported that high levels of RACK1 mRNA expression were associated with a good clinical outcome after a median follow-up of 10 years." (PMID 30962803, 2019). "Also, genes encoding a translation elongation factor, eEF1 and RACK1 (receptor for activated C kinase), were expressed at a lower level in samples from cancer patients, indicating reduced protein translation activity in these samples." (PMID 16168108, 2005). "Alterations in RACK1 homeostasis is associated with brain developmental disorders, heart failure, pulmonary arterial hypertension, renal failure, muscle atrophy and dysfunctional sperm development, as well as cancer and addiction (detailed in sections 6.1 and 6.2)." (PMID 21978545, 2011). "Subjects with high expression of RACK1 & RPS6 were significantly associated with reduced overall (OS), disease-free (DFS), and cancer-specific survival (CSS) (p < 0.001)." (PMID 42058466, 2026). "It has been reported that the B-box domain of TRIM45 is important for the interaction with receptor for activated C kinase 1 (RACK1) in cancer cells." (PMID 40593126, 2025). "Previous research has shown that RACK1 can act as either a tumor suppressor or an oncogene, depending on the cancer type, Moreover, elevated RACK1 expression promotes the malignant progression of HCC." (PMID 39891099, 2025). "Accordingly, RACK1 is involved in diverse biological events such as the immune response, neuronal activity, development, epithelial barrier maintenance and cancer development and progression." (PMID 39846545, 2025). "RACK1's role in cancer progression is complex and context-dependent, acting as both a tumor suppressor and an oncogene in different types of cancers." (PMID 40060229, 2025). "Intriguingly, antibody library screening has identified an anti-RACK1 antibody that effectively suppresses cancer cell proliferation, though its precise molecular mechanism and which specific RACK1 hub it disrupts remain unestablished." (PMID 41373878, 2025). "A total of 10 pairs with high expression of CPNE3 and 11 pairs with high expression of RACK1 were found in cancer tissue." (PMID 41190648, 2025). "This happens through an NF-κB/c-Rel-related mechanism, as the presence of three consensus NF-κB-responsive elements was detected in the RACK1 promoter region, whose positive regulation has also been found in other contexts, including cancer." (PMID 39846545, 2025). "In this study, we discovered that the receptor for activated C kinase 1 (RACK1) regulates cancer cell growth." (PMID 39458945, 2024). "RACK1 stands out as an intriguing target in cancer research due to its complex, context-dependent role." (PMID 39458945, 2024).
cancer (continued). "We developed a specific ScFv antibody for RACK1, which has been shown to inhibit cancer growth and migration while inducing G0/G1 phase arrest in cells." (PMID 39458945, 2024). "RACK1 has gained attention as a promising target for cancer therapy due to its involvement in many key cellular functions." (PMID 39458945, 2024). "To examine if there was an interaction between the H9 antibody and RACK1 to inhibit cancer cell growth, we used four siRNAs (siRACK1#1–4), a silence control, and a control to knock down RACK1 in HepG2, HT29, HCT116, and DU145 cells." (PMID 39458945, 2024). "We discovered new antigens for the H9 antibody, particularly the antigen receptor for activated C kinase 1 (RACK1), which is notably important in regulating several cellular mechanisms in cancer." (PMID 39458945, 2024). "As a scaffold protein, RACK1 links different signaling pathways that control processes like cell growth, migration, and survival, which cancer often manipulates to promote its progression." (PMID 39458945, 2024). "This innovative approach not only deepens our understanding of RACK1′s role in cancer progression but also paves the way for new targeted therapies across a wide range of malignancies and other difficult-to-treat conditions." (PMID 39458945, 2024). "RACK1 is upregulated in a variety of human cancers and has been suggested to contribute to the development and progression of human cancers." (PMID 38451046, 2024). "Of these, BSG/CD147, HEBP2, HSD17B12, and GNB2L1/RACK1 have well characterised functions in cancer and cell survival." (PMID 38398114, 2024). "This correlation suggests enhanced RACK1 stability, exacerbating cancer progression and adversely affecting patient prognosis." (PMID 39697237, 2024). "Since siRACK1 #1 and 2 were successful in diminishing RACK1 levels in these cancer cell lines, we treated the cells with the H9 antibody after the RACK1 silencing." (PMID 39458945, 2024). "In patients with androgen-independent PCa, TRPM7 enhances hypoxia-induced malignant migration and invasion of cancer cells by impeding the degradation of HIF-1α mediated by the receptor for Activated C Kinase 1 (RACK1)." (PMID 39633507, 2024). "As a result, a systematic meta-analysis is required to better understand RACK1’s involvement in cancer prognosis as well as its predictive value, improving clinical decision-making." (PMID 37601269, 2023). "Of these, 13 studies evaluated the predictive value of RACK1 for cancer prognosis, and 20 studies assessed the correlation between RACK1 expression and clinicopathological features." (PMID 37601269, 2023). "In the future, more well-designed studies are warranted to validate the value of RACK1 as a prognostic factor for cancer compared to other recognized typical markers." (PMID 37601269, 2023). "We found that cancer patients with high RACK1 expression exhibited a higher tendency for lymphatic invasion/N+ stage." (PMID 37601269, 2023). "Although RACK1 has been implicated in the initiation and progression of many tumors, the exact function of RACK1 in cancer cellular processes, particularly in proliferation, remains controversial." (PMID 37848434, 2023). "Collectively, these results are consistent with the notion that RACK1 is a functional effector of SMURF2 in cancer." (PMID 37828084, 2023). "The purpose of this review was to clarify the prognostic value of RACK1 expression in cancer and its correlation with the clinicopathological characteristics of patients with cancer." (PMID 37601269, 2023). "As a result, this study aimed to explore the clinicopathological and prognostic values of RACK1 expression in patients with cancer." (PMID 37601269, 2023). "In this regard, the Receptor for Activated C Kinase 1 (RACK1) has been pinpointed as an important biomarker for BC, since its expression directly correlates with overall survival and cancer hallmarks, and it holds high potential as a prognostic value." (PMID 37895012, 2023).
cancer (continued). "Numerous studies have investigated the relationship between RACK1 expression and the prognosis and clinicopathological characteristics of patients with cancer; however, conflicting conclusions have been drawn." (PMID 37601269, 2023). "Aberrant expression of RACK1 has been observed in several kinds of cancers, and it was demonstrated to exert either suppressive or more commonly promotive effects on cancers." (PMID 37591850, 2023). "Further mechanistic studies of the TRIM26-induced cancer-inhibiting effects revealed that TRIM26 regulates MEK/ERK signaling by promoting the degradation of RACK1." (PMID 37591850, 2023). "In future work, it will be crucial to screen and identify SMURF2-specific agonists that activate SMURF2 activity in cancer cells to inhibit RACK1-dependent OC progression." (PMID 37828084, 2023). "Of note, the specificity of RACK1 interaction with circRNAs is expected for at least some of its regulation and biological function in cancer cells, which require further studies." (PMID 36658304, 2023). "Multiple studies have reported that RACK1 is closely related to cancer prognosis; however, its role in cancer prognosis remains controversial." (PMID 37601269, 2023). "RACK1 exerts its roles in several cellular contexts, including the immune system, cancer cells, intestinal homeostasis and neurons." (PMID 37047617, 2023). "For example, it has been demonstrated that Rack1 is highly expressed by activated HSC and upregulated in HCC, moreover, Rack1 can promote self-renewal of cancer stem cells in patients with HCC." (PMID 35093101, 2022). "Previous studies have demonstrated the critical roles of RACK1 in regulating the processes of cancer cell proliferation, adhesion, migration, invasion and metastasis." (PMID 35957886, 2022). "Although many studies have reported the crucial role of RACK1 in tumorigenesis, its biological function varies in different types of cancers." (PMID 35101055, 2022). "It has also been demonstrated that Rack1 promotes non‐small‐cell lung cancer (NSCLC) tumorigenicity by activating Smoothened to mediate Gli1‐dependent transcription in cancer cells." (PMID 34480519, 2021). "Current studies have confirmed that RACK1 (receptor for activated C kinase 1) is a scaffold protein, which is upregulated in many human cancers, including OSCC24–26." (PMID 33723221, 2021). "We provide an analysis of immunomodulatory and cancer-promoting effects of different EDCs in shaping tumour microenvironment, with a final focus on the scaffold protein RACK1 as a pivotal molecular player due to its dual role in immune and cancer contexts." (PMID 33287384, 2020). "The cancer-associated BRCA1 variants R133H and E143K, and the RACK1 variant K280E, which decrease the binding of BRCA1 to RACK1, suppress the centrosomal localization of BRCA1." (PMID 32722046, 2020). "In light of EDCs as drivers of TME-promoted cancer phenotype and RACK1 role as both EDCs target and signalling hub in the cancer context, we propose investigating RACK1 as a possible dual-role molecular player in TME." (PMID 33287384, 2020). "In this review, we discussed RACK1 dual role as a possible molecular bridge for cell response to EDCs in immune and cancer system." (PMID 33287384, 2020). "A complex hormonal balance between glucocorticoids and androgens has been demonstrated to control RACK1 expression in both the immune and the cancer context." (PMID 33311444, 2020). "This is particularly relevant in cancer context, since RACK1 has been demonstrated to directly bind FAK and this complex is recruited at focal adhesion level for cancer cell migration and invasion." (PMID 33287384, 2020). "Taken together, our study demonstrated that the Rack1 plays dual roles in Hh pathway, and provided Rack1 as a prudent drug target for Hh-related cancers." (PMID 32467643, 2020).
cancer (continued). "Deregulated expression of Rack1 has been reported in many types of carcinoma, and the function of Rack1 on cancer invasion and metastasis appears cancer type- and cell context-specific." (PMID 31113450, 2019). "RACK1 gene knock-down or mRNA/protein depletion in higher eukaryotes is lethal during early embryogenesis, and medical studies have provided ample evidence that aberrant RACK1 expression in mammals coincides with different types of cancer." (PMID 31689955, 2019). "Our findings suggest a convergence point role of Rack1/Src/Anxa2 complex in the crosstalk between drug resistance and cancer aggressiveness." (PMID 31113450, 2019). "In summary, our study demonstrated a pivotal role of Rack1 involved in the crosstalk between drug resistance and cancer invasion/metastasis." (PMID 31113450, 2019). "Previous studies have shown that the interaction between RACK1 and c-Src regulates the proliferation of cancer cells." (PMID 31358728, 2019). "The receptor of activated protein kinase C 1 (RACK1) promotes the progression and invasion of several cancers." (PMID 30962803, 2019). "Recently, Rack1 has been reported to be a key protein involved in drug resistance in several carcinomas." (PMID 31113450, 2019). "As can be expected from RACK1's important role in the cell cycle, there are many reports of altered RACK1 expression in variety of cancers." (PMID 30112187, 2018). "When RACK1 levels are depleted, aberrant signalling can affect important cellular processes such as cancer cell growth and T cell migration." (PMID 30112187, 2018). "This dual process relies on two distinct mechanisms, the first of these being the direct suppression of Src activity by RACK1, leading to attenuation of mitotic exit and entrapment of cancer cells in G2/M phase." (PMID 30112187, 2018). "RACK1 is upregulated in the various types of human cancers, and considered to play a role in the development and progression of human cancer." (PMID 30451832, 2018). "It has also been reported that RACK1 promotes growth in other cancers by affecting key cell cycle regulators." (PMID 28465488, 2017). "Using a blocking peptide approach, we were able to prevent the plasma membrane mobilization of NHE6, by reducing its binding to the scaffold RACK1, leading to the reversal of endosome hyperacidification and cancer cell sensitization to Dox." (PMID 28635961, 2017). "Several studies demonstrated that Rack1 was a key enhancer in cancer cell proliferation and invasion." (PMID 27754360, 2016). "By contrast, other studies have shown that Rack1 functions as a suppressor in growth, invasion and metastasis in several types of cancer." (PMID 27754360, 2016). "Emerging studies show that dysregulation of the receptor of activated protein kinase C1 (RACK1) plays a crucial role in tumorigenesis and progression of various cancers." (PMID 27763568, 2016). "Some researchers have found that RACK1 not only participated in the morphology characteristic of adhesion through the formation of focal adhesions and stress fibers in some cancer cells, but also played an important role in cell migration." (PMID 27763568, 2016). "Because RACK1 downregulats cell apoptosis by regulating Src/Akt activity, we first examined the activation states of Src and Akt after anti-cancer treatment or X-ray treatment in NHE9-overexpressing and NHE9 knockdown cells." (PMID 25915159, 2015). "Consistent with this, it was shown by others that RACK1 regulates cell adhesion, moreover, silencing of RACK1 inhibited cell proliferation and decreased migration and adhesion capability of carcinoma cells." (PMID 23305203, 2013). "Many reports indicate that RACK1 plays an important role in cancer progression and that its expression is altered during angiogenesis and in many human carcinomas." (PMID 21978545, 2011). "Recent results linking reduced global expression of miRNAs and reduced miRNA function with tumorigenesis encouraged us to examine RACK1 expression in cancers." (PMID 21935400, 2011).